CTCF (CCCTC-binding factor)
Diseases named in the same sentence as CTCF in open-access papers (continued):
Sharing a sentence is not in itself a finding about the gene and the disease.
infection (32 papers, 2004 to 2025). The state of being infected such as from the introduction of a foreign agent such as serum, vaccine, antigenic substance or organism. "Finally, the association of repressive proteins, such as CTCF, is dynamic to allow for acute infection, latency, and reactivation." (PMID 39431845, 2024). "It is possible that changes in epigenetic modifications would take a longer time to become established after the provirus is mutated, or that CTCF imposes an epigenetic boundary at the pX region in the early stage of infection and becomes dispensable thereafter." (PMID 30607369, 2018). "A limitation of the current work is that the temporal regulation of Tax expression by CTCF during the first five days of infection was performed in tissue culture models and remains to be confirmed in vivo." (PMID 40460345, 2025). "Compared with mock infection, changes in the binding of CTCF and RAD21 and histone modifications after IAV infection and IFN-β treatment were finally measured by the proportions of intervals having different binary values." (PMID 39202349, 2024). "In the context of HSV-1 infection, global CTCF knockdown during the lytic infection led to a reduction of RNAPII occupancy on viral promoters, suggesting a link between RNAPII recruitment and CTCF enrichment on the viral genome." (PMID 39374265, 2024). "In agreement with our earlier data with HepG2-HBV-Epi cells, CTCF depletion in this de novo infection model increased total transcripts and preC/pgRNA levels." (PMID 33006186, 2021). "CTCFL, the gene encoding the CTCF-homolog BORIS, is also significantly increased over the course of infection, while CTCF itself remains stable." (PMID 33497421, 2021). "ATAC-seq analysis of cellular chromatin showed that EBV alters over a third of accessible chromatin during the infection time course, with many of these sites overlapping transcription factors such as PU.1, Interferon Regulatory Factors (IRFs), and CTCF." (PMID 33497421, 2021). "To extend our studies and to validate a role for CTCF in repressing viral transcription during a de novo infection, we silenced CTCF in HBV infected HepG2-NTCP cells." (PMID 33006186, 2021). "We chose two CRC cell lines (HCT-116 and RKO) to construct CTCF-overexpressing cell lines via lentivirus infection." (PMID 32688344, 2020). "For this reason, we have chosen HeLa cells to do further functional analysis of CTCF knockdown on HSV-1 lytic infection." (PMID 28045091, 2017). "This suggests that HPV18 and perhaps other oncogenic HPV types have evolved to bind CTCF in this region to regulate balanced and controlled E6 and E7 expression in the context of a productive infection." (PMID 25694598, 2015). "This indicates that the CTCF-cohesin binding site is important for viral gene regulation in latently infected 293T cells and during primary infection of endothelial cells." (PMID 21876668, 2011). "To further parse out how an individual functional CTCF insulator contributes to the initial chromatinization and transcription of viral genes during the lytic infection, we leveraged our ΔCTRL2 recombinant virus in a series of experiments designed to determine the role of the CTRL2 insulator." (PMID 39374265, 2024). "B2 elements have contributed non-coding RNAs inducible by stress or infection, splicing signals, promoter elements, and CTCF-bound insulator elements." (PMID 37158599, 2023). "CCCTC-binding factor (CTCF) is involved in the control of viral gene transcription of several DNA viruses but its potential role during infection by rotavirus, a double-stranded RNA virus, is unknown." (PMID 34205050, 2021). "However, the binding of CTCF to the viral genome and host genome in response to infection by other viruses has been observed." (PMID 34940755, 2021). "To assess whether infection perturbs CTCF expression, we analysed a publically available Affymetrix microarray database from chronic HBV infected patients." (PMID 33006186, 2021).
infection (continued). "Noticeably, the motifs for NF-κB [which binds to DNA and becomes transcriptionally active upon infection and inflammation; 41, 42], and CTCF [which establishes discrete functional chromatin domains by promoting DNA looping; 43, 44, 45] were enriched at enhancers targeting non-expressed genes." (PMID 29300726, 2018). "In addition, CTCF mRNA levels were knocked down by stable infection of lentiviral shRNA specific to CTCF in HCTE cells." (PMID 27583466, 2016). "To determine whether CTCF binding to the HSV-1 genome is dynamic during lytic infection, we also did ChIP-qPCR to measure CTCF binding at different time points after the infection, and found that there is significant occupancy of CTCF on the tested sites among 2, 4 and 6 hpi samples." (PMID 28045091, 2017). "ChIP-seq experiments for TEAD1, CTCF, and H3K27ac were performed in duplicate in uninfected and HCMV-infected conditions (48 hr post-infection)." (PMID 40928347, 2025). "Footprint analysis of ATAC peaks also revealed slight increases in signals for CTCF and CTCFL transcription factors following infection." (PMID 40539063, 2025). "The CTCF sgRNA domain library was cloned into a lentiviral vector with puromycin resistance and CFP fluorescence followed by infection at a low M.O.I. (less than 0.3) into a SEM B-ALL cell line stably expressing Cas9." (PMID 36698211, 2023). "We found cytokines like IFNγ, IL-4, IL-13, IFNβ1, TNFα, and transcriptional regulators such as HIF1α, STAT1, CTCF, TP73, IRF1, MXD1, ATF4, SPI1 mediate macrophage activation upon infection." (PMID 35789215, 2022). "As predicted by the motif enrichment analysis of differentially accessible chromatin, regions where the chromatin closed with infection did not contain CTCF ChIP-seq peaks." (PMID 40928347, 2025). "In contrast, the total number of CTCF peaks was largely consistent with and without infection (54,697 vs. 57,936 peaks)." (PMID 40928347, 2025). "Another interesting observation was the identification of CTCF/BORIS sites within cluster 1, which was the only cluster in which Day 0 had the highest signal for all ATAC peaks, implying a significant closing of the DNA immediately after infection." (PMID 33497421, 2021). "To evaluate the role of CTCF in vivo, we compared the abilities of 729, 729.HTLV-1, 729.HTLV-1∆CTCF, or 729.HTLV-1p12Stop cell lines to transmit virus to rabbits, which is an established model of infection and persistence." (PMID 31864373, 2019). "To explore the spatial relationship between CTCF and HSV-1 genome, we performed super resolution immunofluorescence microscopy (Nikon N-SIM) imaging in human primary fibroblast BJ cells at 6 hours post infection (hpi)." (PMID 28045091, 2017). "Previous results have shown that CTCF can bind and suppress MIE gene expression during lytic infection of fibroblasts, so we predicted that this function could be of major importance in latently infected monocytes where general suppression of major IE expression occurs." (PMID 34042564, 2021). "We then speculated that the virally encoded G protein coupled receptor US28 may play a role in CTCF upregulation, because (i) CTCF was previously shown to repress MIEP activity during lytic infection and (ii) a key role of US28 during latency is the negative regulation of the MIEP." (PMID 34042564, 2021). "Interestingly, since NS1 is not present in the early steps of infection, other proteins such as the viral protein of the capsid or the cellular proteins CTCF or MDC1, may be involved if localization of MVM at DNA damage sites occurs at the earliest stage of infection." (PMID 35216038, 2022). "To exclude the possibility that interfering with CTCF expression affects HCMV binding/entry and the earliest events of infection, rather than IE gene expression itself, we analysed HCMV genome levels in CTCF overxpressing, CTCF knockdown, and relevant control cells." (PMID 34042564, 2021).
neurodevelopmental disorder (11 papers, 2018 to 2025). A behavioral and cognitive disorder with onset during the developmental period that involves impaired or aberrant development of intellectual, motor, or social functions. "Subsequently, several studies reported numerous pathogenic CTCF variants in patients with ID and neurodevelopmental disorders." (PMID 37664546, 2023). "CTCF variants cause neurodevelopmental disorders, sometimes associated with recurrent infections and minor facial dysmorphisms." (PMID 36250618, 2022). "CTCF, a well-known regulator of chromatin structure, has been implicated in various neurodevelopmental disorders." (PMID 36052683, 2022). "We demonstrate that removing the target exon significantly increased protein translation (between 1.4-5.5 fold) in a luciferase reporter assay for four of six prioritised target 5’UTR exons in neurodevelopmental disorder genes (CTCF,GRIN2B,KRIT1, andTSC1)." (PMID 41573882, 2025).
neurodegenerative disease (4 papers, 2021 to 2025). A disorder of the central nervous system characterized by gradual and progressive loss of neural tissue and neurologic function. "Another important consideration is the likely adverse impact of environmental toxins on the diverse functions of CTCF and how this might contribute to impaired biological processes and degenerative diseases." (PMID 33411704, 2021). "Our results revealed the important role of CTCF during normal development and in maintaining PCs and provide new insights into the molecular mechanism of GLB formation during neurodegenerative disease." (PMID 36447271, 2022).
genetic disease (3 papers, 2018 to 2024). "CTCF was identified as one of nearly 300 haploinsufficient genes in humans based on published literature or a clear association with genetic disease." (PMID 30513694, 2018). "However, only a small number of genetic diseases where CTCF site-specific mutations lead to alterations of these enhancer–promoter interactions have been reported." (PMID 33863876, 2021).
blood disorders (2 papers, 2025). "The newly identified repressive role of CTCF might have a significant function in blood development and related blood disorders, which needs further characterization." (PMID 40022213, 2025).
breast (2 papers, 2018 to 2025). "Recently, it has been shown that lncRNA OGFRP1 mediates the formation of CTCF by means of miR-423-5p, which in turn promotes colorectal carcinogenesis, metastasis, and angiogenesis." (PMID 41502505, 2025).
cardiovascular disease (2 papers, 2021 to 2022). "We constructed an mRNA–miRNA–lincRNA ceRNA interaction network centered on miR-22-3p and used the starBase v2.0 and miRWalk databases to predict eight related transcription factors associated with cardiovascular disease, namely, CTCF, JUN, JUND, NFATC1, NFE2L2, RAD21, RELA, and TAL1." (PMID 36105099, 2022). "CTCF, which is a highly conserved zinc-finger DNA-binding protein, has been found to play a role as a transcriptional repressor of the Myc gene and to be involved in the occurrence of various cardiovascular diseases." (PMID 33934724, 2021).
heart disease (2 papers, 2025 to 2026). "The role of CTCF-associated rewiring in heart disease and its association with pathological gene expression thus remains unresolved from our point of view." (PMID 41526351, 2026). "In conclusion, this study revealed the molecular mechanism underlying heart abnormalities in CTCF‐R567W mice, which is of great significance for understanding the pathogenesis of heart disease and for future diagnosis and treatment strategies." (PMID 39682078, 2025). "Several attempts to explore the role of CTCF and cohesin in maintaining chromatin structure and function in heart disease in mice resulted in contrasting observations." (PMID 41526351, 2026).
neurological disorders (2 papers, 2022 to 2025). "Likewise, understanding the mechanisms by which CTCF regulates locus‐specific gene expression will illuminate underlying mechanisms of neurological disorders and likely help to increase our understanding of oncogenesis." (PMID 35993175, 2022).
brain disorder (1 paper, 2020). A disease affecting the brain or part of the brain. "Given that CTCF mutations or variants dysregulate cPcdh genes, it’s likely that this cPcdh dysregulation is responsible for complex brain disorders caused by CTCF mutations or variants." (PMID 33262685, 2020).
infectious disease (1 paper, 2024). A disorder directly resulting from the presence and activity of a microbial, viral, or parasitic agent in humans. "An alternative interpretation is that the increased levels of antibodies against EBNA6_0488 resulted from a putative CTCF overexpression during the disease progression in the cohort of ME/CFS patients with an infectious disease trigger." (PMID 38256421, 2024).
renal disease (1 paper, 2023). "The assembly of gene-activating events by CTCF and Pol2B helps to partly explain the high affinity for unmethylated regions in T1D individuals with progressive renal disease." (PMID 36633903, 2023).
CTCF also shares sentences with these, for which no sentence is quoted: microcephaly (7 papers); Wilms' tumors (3); acute leukemia (2); autism spectrum disorder (2); clear cell renal cell carcinoma (2); colon (2); HIV-1 infection (2); medulloblastoma (2); psychiatric disorder (2); skin melanomas (2); uterine carcinosarcoma (2); acute graft versus host disease (1); acute pancreatitis (1); adult T cell leukemia (1); anemia (1); Angelman syndrome (1); astrocytoma (1); attention deficit-hyperactivity disorder (1); autosomal dominant mental retardation (1); behavior (1); blood cancers (1); breast adenocarcinoma (1); chronic lymphocytic leukemia (1); cognitive disorder (1); colorectal adenocarcinoma (1); dementia (1); diffuse midline glioma (1); ependymoma (1); Fibroadenoma (1); folate deficiency (1).
A further 37 diseases each share a sentence with CTCF in 1 paper.